RN7SKP156 (RN7SK pseudogene 156)
Gene: Miscellaneous RNA gene on chromosome 1 (188,155,839 to 188,156,180, reverse strand). Ensembl gene ENSG00000222240.
Homologues: Orthologues: chimpanzee 7SK (99% identical). Paralogues in human: 7SK (68% identical), RN7SKP174 (65% identical), RN7SKP187 (65% identical), RN7SKP118 (64% identical), RN7SKP48 (64% identical), RN7SKP62 (64% identical), RN7SKP160 (64% identical), RN7SKP184 (64% identical), RN7SKP185 (64% identical), RN7SKP269 (63% identical), RN7SKP178 (62% identical), RN7SKP25 (62% identical), and 283 more.